MYC (MYC proto-oncogene, bHLH transcription factor)
Diseases named in the same sentence as MYC in open-access papers (continued):
Sharing a sentence is not in itself a finding about the gene and the disease.
endothelial dysfunction (6 papers, 2013 to 2025). In vascular diseases, endothelial dysfunction is a systemic pathological state of the endothelium (the inner lining of blood vessels) and can be broadly defined as an imbalance between vasodilating and vasoconstricting substances produced by (or acting on) the endothelium. "In endothelial cells, downregulation of MYC activates a pro-inflammatory senescence phenotype and can act as a regulator of inflammation and endothelial dysfunction." (PMID 36578501, 2022). "Abnormal expression of MYC is closely related to inflammatory responses and endothelial dysfunction, which may be an important link in the pathogenesis of VTE." (PMID 41210882, 2025).
erythroleukemia (6 papers, 2013 to 2025). Acute erythroid leukemia characterised by the presence of at least 50% erythroid precursors and at least 20% myeloblasts in the bone marrow. "Similar to MYCN expression, MYC expression was also higher in the patients with erythroleukemia, M2 or M5 (all P<0.05) compared with the normal controls." (PMID 29022893, 2017). "Considering the pivotal role of MYC in erythroleukemia development, we explored the biological function of MYCN in erythroleukemia cell lines HEL and K562." (PMID 29022893, 2017).
kidney tumor (6 papers, 2006 to 2022). "Like the patient’s kidney tumor, the lung metastasis was also classified as MYC subgroup based on methylation profiling, further supporting the probable shared clonal origin of these two extracranial tumors." (PMID 35912263, 2022). "To better characterize the phenotype of the kidney tumours from MYC mice we generated two cell lines from separate MYC tumours (MYC-2927 and MYC-2983)." (PMID 28593993, 2017). "Methylation profiling classified both as MYC, supporting the abdominal metastases that share similar epigenetic features to the kidney tumor and therefore may share a clonal origin." (PMID 35912263, 2022). "However, in contrast to Schroff and colleagues our MYC mice developed renal tumours with histology highly reminiscent of human papillary RCC." (PMID 28593993, 2017). "A previous study in genetically engineered mouse models had found that MYC activation with CDKN2A deletion and VHL deletion together produce kidney tumors that closely resemble human clear cell RCC41." (PMID 33547292, 2021). "MYC activation results in highly penetrant pRCC tumours (MYC), while MYC activation, when combined with Vhl and Cdkn2a (Ink4a/Arf) deletion (VIM), produce kidney tumours that approximate human ccRCC." (PMID 28593993, 2017). "These observed molecular differences between the brain and kidney tumors is further supported by their classification into different methylation subgroups (SHH and MYC, respectively), indicating that the tumors do not share a clonal origin." (PMID 35912263, 2022).
liver cirrhosis (6 papers, 2017 to 2024). "Activation of MEK‐ERK‐c‐MYC signaling pathway promotes splenic M2-like macrophage polarization to inhibit PHcH-liver cirrhosis." (PMID 39620221, 2024). "MYC promotes the progression of liver cirrhosis by upregulating the inflammatory factors IL8, IL10, and TGFβ." (PMID 28355233, 2017). "Some of the important hub genes in the BisoGenet-derived PPI for liver cirrhosis and HCC diseases were E2F1, TAL1, CEBPB, ELF1, RAD21, CEBPB, and MYC." (PMID 35265561, 2022).
lymphedema (6 papers, 2013 to 2025). Excess fluid collection in tissues, causing swelling. "Recent advances in molecular profiling, such as detecting MYC amplification - a near-specific marker for sAS associated with prior radiation or lymphedema, highlight the critical role of integrating genomic biomarkers with IHC." (PMID 40666093, 2025). "Nonetheless, the strong preference for MYC amplification in sAS compared to pAS suggests a distinct pathogenic mechanism in the context of underlying lymphedema or prior radiation." (PMID 40666093, 2025). "This similarly identified MYC amplification as exclusive to 5 radiation-associated AS and 1 lymphedema-associated AS, and noted MYC overexpression by IHC in the absence of MYC amplification in 1 primary AS case." (PMID 33182685, 2020). "The status of the c-MYC gene should therefore be further evaluated in the specific situation of chronic congenital lymphedema." (PMID 24078891, 2013). "FISH in an expanded cohort of 28 primary AS, 31 radiation-associated AS, and 2 lymphedema-associated AS cases detected MYC amplification in 55% of secondary AS, but not in primary AS; indicating MYC amplification is exclusive to secondary AS, and detectable irrespective of aetiology." (PMID 33182685, 2020).
marginal zone lymphoma (6 papers, 2012 to 2026). A usually indolent mature B-cell lymphoma, arising from the marginal zone of lymphoid tissues. "Parallel studies of mouse cell lines established from primary small B cell lymphomas (SBL), DBLL and splenic marginal zone lymphomas (MZL) showed that ARF-BP1 was expressed at uniquely high levels in MYC-driven DBLL." (PMID 22754359, 2012).
metastasis (6 papers, 2021 to 2026). The spread or migration of cancer cells from one part of the body (where they first appeared) to another. "Genomic analysis revealed site-specific correlations: MYC mutations with pleural metastasis, NTRK3 with brain metastasis, ALK with adrenal metastasis, and NTRK1 with intrapulmonary metastasis." (PMID 42187573, 2026). "Conversely, liver metastasis and specific mutations in MYC and MLL2 genes were associated with a poor response to ICIs across all patient groups." (PMID 40867302, 2025).
pulmonary fibrosis (6 papers, 2013 to 2022). Chronic progressive interstitial lung disorder characterized by the replacement of the lung tissue by connective tissue, leading to progressive dyspnea, respiratory failure, or right heart failure. "Research has shown that MYC is up-regulated in pulmonary fibrosis cells of IPF mice and promote the growth and differentiation of pulmonary fibrosis cells by regulating the transcription of miR-9-5p." (PMID 36601116, 2022). "MYC may promote the exacerbation of pulmonary fibrosis according to immune regulation, and be a key gene according to the interaction network." (PMID 34983465, 2022). "In a TGF-β-induced lung fibrosis model in rats, TGF-β inhibited cell proliferation by suppressing MYC expression." (PMID 36578501, 2022).
rectal tumors (6 papers, 2014 to 2022). "Ribosome biogenesis is directly regulated by c-MYC, and GSEA showed that the genes specifically overexpressed in rectal tumors are targeted by c-MYC." (PMID 32824266, 2020). "The confirmed presence of MYC expression in the intended radiotherapy target tissue (primary rectal tumors) in LARC patients encourages future exploration of this proto-oncogene as a novel biomarker endpoint." (PMID 24587009, 2014).
Splenomegaly (6 papers, 2012 to 2021). Abnormal increased size of the spleen. "Diseased Eμ-MYC and Eμ-MYC Chk1+/− mice developed similar splenomegaly whereas spleen weights from tumor-free, aged mice, sacrificed after one year were found unaffected." (PMID 29167438, 2017). "Co-expression of BCL-XL or BCL-2 together with MYC resulted in splenomegaly in all animals with mean values for moribund animals at 757 mg for BCL-XL/MYC BALB/c and 899 mg for BCL-2/MYC BALB/c mice." (PMID 22393362, 2012). "As in Mock/Myc mice, FLIPL/MYC mice appeared to have a latency period before development of splenomegaly (average spleen weight at 5 weeks after transplantation, 237 mg for FLIPL/MYC compared to 236 mg for Mock/MYC and 138 mg for Mock/Mock recipient mice)." (PMID 22393362, 2012). "Patients with high c-MYC expression and/or low MYCBP2 expression had higher WBC counts and a higher percentage of CD34+ or CD33+ cells, as well as splenomegaly, liver infiltration, higher BM blasts, and lower CR rate." (PMID 26517351, 2015). "The percentage of patients exhibiting splenomegaly, liver infiltration, and increased lactate dehydrogenase (LDH) was significantly higher in the high c-MYC expression group than in the low expression group (53.0% vs 36.1%, P = 0.039; 34.8% vs 15.5%, P = 0.006; 49.2% vs 31.2%, P = 0.033)." (PMID 26517351, 2015). "Mice injected with T20 cells (MYC+AKT+p53DD) from an independent experiment, were euthanized between days 20-40, displayed no signs of lymphadenopathy and splenomegaly was observed only in one out of five mice." (PMID 29765548, 2018).
steatosis (6 papers, 2012 to 2022). Increased lipid within the cytoplasm of cells. "Retroviruses encoding the reprogramming factors, OCT4, SOX2, KLF4, and c-MYC were transduced into fibroblasts cells from patient with steatosis (H0008) and control (H0002) using well established protocols." (PMID 22969728, 2012). "As expected, c-MYC overexpression exacerbated steatosis, liver injury, liver inflammation, fibrosis and strong compensatory proliferation in transgenic mice fed with WD." (PMID 35008356, 2021). "Alteration in CCR7, IMPDH2, IL6ST, MYC, LPIN1, PDE7A and RORA was significantly associated with hepatotoxicity including liver damage, -hyperplasia, -inflammation, -steatosis, -fibrosis, -necrosis and -proliferation." (PMID 26907258, 2016). "Taken together, dysregulation of m6A methylation caused steatosis and fibrosis, affecting the occurrence of NAFLD, and MYC might be its potential target." (PMID 36120320, 2022). "Our findings support the conjecture that MYC is consistently down-regulated in steatosis and NASH patients, MYC may be indispensable for the homeostasis of lipid metabolism." (PMID 33324350, 2020). "Therefore, the dysregulation of m6A methylation caused steatosis and fibrosis affected the occurrence of NAFLD, and MYC might be its potential target." (PMID 36120320, 2022). "Eventually, we determined 10 hub genes (Down-regulated genes: MYC, TGFB3, ADAMTS1, THBS1, RASD1, PCDH20; Up-regulated genes: MAMDC4, CYP7A1, GINS2, and PDLIM3) related to NAS and steatosis." (PMID 34777484, 2021). "Of the top-ranked 10 genes, two genes (CYP7A1 and PEG10) were significantly up-regulated in both steatosis and NASH patients, while eight genes (FOSB, FOS, IL6, GADD45G, MYC, SLITRK3, JUNB, and IGFBP2) were significantly down-regulated." (PMID 33324350, 2020). "However, unlike other findings, MYC expression was decreased in obese and steatosis patients." (PMID 36120320, 2022).
Stroke (6 papers, 2022 to 2025). Sudden impairment of blood flow to a part of the brain due to occlusion or rupture of an artery to the brain. "miRNA-200b-5p negatively regulates SIRT1 translation and is downregulated by myc proto-oncogene protein (MYC, c-myc) in stroke model systems, showing a negative correlation with SIRT1 expression." (PMID 40724883, 2025).
Arthritis (5 papers, 2020 to 2024). Inflammation of a joint. "To address the role of NRF2-MYC axis in osteoclast-mediated pathogenic bone erosion, we tested the effect NRF2 and NRF2/MYC double deficiencies on bone loss in K/BXN serum-induced arthritis." (PMID 32967239, 2020). "MYC conditional deficiency significantly reduced osteoclast number in NRF2 KO mice in a K/BXN serum transfer-induced arthritis model." (PMID 32967239, 2020). "At the same time, exosomes can affect arthritis chondrocyte function and glutamate metabolism by downregulating c-MYC." (PMID 34992497, 2021). "Moreover, it has been suggested that MYC can regulate the production of pro-inflammatory cytokines, such as IL-1 and TNF, which are key drivers of inflammation in arthritis." (PMID 39028255, 2024).
autoimmune disease (5 papers, 2017 to 2023). A disorder resulting from loss of function or tissue destruction of an organ or multiple organs, arising from humoral or cellular immune responses of the individual to their own tissue constituents. "Metabolic reprogramming occurs generally downstream of TCR and the co-stimulatory receptor (such as CD28) signaling following interaction between T cells and APCs in autoimmune disease, which activates mTORC1 and MYC signaling." (PMID 35401560, 2022).
Barrett esophagus (5 papers, 2008 to 2025). Esophageal lesion lined with columnar metaplastic epithelium which is flat or villiform. "In comparison to matched normal gastric controls the expression of c-MYC and MXI1 was significantly upregulated in Barrett's metaplasia; conversely, the expression of MAD1 was significantly lower in the metaplastic lesion than in the normal mucosa." (PMID 18493233, 2008). "When expression in adenocarcinoma was evaluated in comparison to matched Barrett's metaplasia it was apparent that expression of MYC, MXI1 and MAX were significantly elevated in the malignant transformation of Barrett's metaplasia." (PMID 18493233, 2008). "While a difference in MYC and MXI1 was demonstrated between Barrett's metaplasia and adenocarcinoma at the level of mRNA, there was no significant alteration in protein expression in malignancy." (PMID 18493233, 2008).
benign prostatic hyperplasia (5 papers, 2008 to 2021). A non-cancerous nodular enlargement of the prostate gland. "The different effects of GLS1 and MYC inhibition in cancer and benign prostate hyperplasia cells can be in part explained by unique metabolic characteristics of normal prostate epithelial cells such as truncated TCA cycle, OXPHOS-deficiency, and high dependence on glycolysis for energy production." (PMID 34335968, 2021). "Both, GLS and MYC inhibition did not cause toxic effects on benign prostate hyperplasia (BPH) cells." (PMID 34335968, 2021).
breast angiosarcoma (5 papers, 2018 to 2025). A malignant vascular neoplasm arising from the breast. "Primary breast angiosarcomas frequently present with PI3K pathway mutations, while secondary radiation and lymphedema-associated tumors are more likely to present with MYC amplifications." (PMID 41301029, 2025). "MYC gene amplification is highly indicative of secondary breast angiosarcomas." (PMID 35456944, 2022). "Recent evidence has implicated amplification of the 8q24.2 region containing the MYC gene in secondary but not in primary breast angiosarcomas." (PMID 29515789, 2018).
cutaneous squamous cell carcinoma (5 papers, 2018 to 2024). "Moreover, in skin, the lncRNA MALAT1 was shown to interact with the transcription factor MYC and bind to the promoter region of the Kinectin 1 (KTN1) gene, thus contributing to enhancement of epidermal growth factor (EGF) signaling in cutaneous squamous cell carcinoma." (PMID 38542324, 2024).
ductal carcinoma in situ (5 papers, 2009 to 2024). "MYC gain and PTEN loss were significantly associated with the presence of intraductal carcinoma at biopsy by logistic regression analyses (OR, 13.33; 95% CI, 3.85–49.67; P < 0.0001 for combined MYC gain and PTEN loss)." (PMID 34062284, 2021). "Of interest, addition of joint MYC and PTEN status at biopsy to the baseline model that included age, PSA, clinical stage, proportion of positive cores, presence of cribriform or intraductal carcinoma, and percentage of Gleason pattern 4 carcinoma further increased the AUC to 0.75." (PMID 34062284, 2021).
embryonal tumors (5 papers, 2015 to 2025). "Our results using a cyclin D1-dependent hematologic malignancy, a MYC-dependent embryonal tumor, and a PI3K-dependent solid tumor demonstrate that SRX3177 is efficacious and non-toxic in vitro to normal epithelial cells." (PMID 32793389, 2020). "To characterize the effect of SRX3177 in detail, we measured cytotoxic activity of this inhibitor in a cyclin D1-dependent hematologic malignancy (mantle cell lymphoma), a MYC-dependent embryonal tumor (neuroblastoma), and a PI3K-dependent solid tumor (hepatocellular carcinoma)." (PMID 32793389, 2020). "Future trials using chemotherapy should really focus on pediatric CNS embryonal tumors known to be chemosensitive but for whom the ideal combination has not yet been identified, specifically MYC-amplified group 3 MB, recurrent MB, and young children with radiation-sparing approaches." (PMID 40710220, 2025).
gastritis (5 papers, 2012 to 2025). Inflammation of the stomach. "A significantly higher MYC mRNA expression was observed in intestinal metaplasia compared to gastritis samples." (PMID 22768805, 2012). "Tukey post-hoc analyses revealed that MYC mRNA expression was higher in intestinal metaplasia than superficial (p < 0.001) and atrophic (p < 0.001) gastritis." (PMID 22768805, 2012). "On the other hand, MYC immunoreactivity was described in gastritis samples, as well as intestinal metaplasia, in Asian populations." (PMID 22768805, 2012). "It is also reported that significantly higher MYC expression was observed in IM samples than gastritis samples from cancer-free individuals and this may facilitate tumor initiation." (PMID 33259779, 2021).
gastrointestinal stromal tumor (5 papers, 2017 to 2025). "In addition, genomic inactivation of MAX has been recently associated with an MYC-independent progression to malignancy of gastrointestinal stromal tumors, and future studies might reveal the contribution of the clock function of MAX in its paradoxical tumor suppressor role." (PMID 32225100, 2020).
HIV-1 infection (5 papers, 2021 to 2026). The type species of lentivirus and the etiologic agent of acquired immunodeficiency syndrome (AIDS). "More recently, HIV-1 infection was found to strongly downregulate MYC and downstream targets as part of transcriptomic remodeling, in line with our finding that MYC-dependent programs are suppressed in DCs with transcriptionally active HIV-1." (PMID 41596493, 2026). "This interaction suggests a potential downregulation of MYC expression upon HIV-1 infection of macrophages." (PMID 40453371, 2025). "Conversely, it can be hypothesized that the reduced expression of MYC during HIV-1 infection may attenuate the repression of HIV-1, potentially facilitating viral replication and propagation." (PMID 40453371, 2025).
Hypertension (5 papers, 2020 to 2023). The presence of chronic increased pressure in the systemic arterial system. "GSEA and functional enrichment of gene module of interest have indicated that “Heme metabolism,” “TNF alpha/NFkB,” and “interferon alpha response signaling,” and MYC target v1/v2 were enriched significantly in different stages of hypertension progression." (PMID 36277786, 2022). "Gut dysbiosis increases intestinal MYC expression and aggravates hypertension and anxiety." (PMID 37273529, 2023). "Gut dysbiosis leads to hypertension and anxiety by reducing short-chain fatty acids, vitamin D, and 5-hydroxytryptamine (5-HT), and increasing trimethylamine N-oxide (TAMO) and MYC." (PMID 37273529, 2023). "The effect of estrogen, androgen and cytokines are reflected on clusters of estrogen and androgen receptors, STAT5, JUN, MYC and other TFs binding at ACE2 regulatory regions, where hypertension QTLs and the great majority of ACE2 eQTLs are also mapped to." (PMID 32558150, 2020).